MAST1 (microtubule associated serine/threonine kinase 1)
Description:
Microtubule-associated protein essential for correct brain development. Appears to link the dystrophin/utrophin network with microtubule filaments via the syntrophins. Phosphorylation of DMD or UTRN may modulate their affinities for associated proteins (By similarity).
Synonyms: KIAA0973; SAST; MCCCHCM
Tractability: Small molecule: a structure with a bound ligand is known; a high-quality ligand is known; it belongs to a druggable protein family. Antibody: UniProt places it where antibodies can reach, with medium confidence; its Gene Ontology location is reachable by antibodies, with medium confidence. PROTAC: ubiquitination databases record sites on it; its protein half-life has been measured; a small molecule that binds it is known.
Target class: Enzyme; AGC protein kinase group; Protein Kinase; Kinase; AGC protein kinase MAST family
Gene: Protein-coding gene on chromosome 19 (12,833,951 to 12,874,952, forward strand). Ensembl gene ENSG00000105613.
Subcellular location: Cell membrane; Cytoplasm, cytoskeleton; Cell projection, axon; Cell projection, dendrite
Subcellular location (Human Protein Atlas): Vesicles; Cytosol
Gene Ontology:
Molecular function: protein binding; ATP binding; magnesium ion binding; microtubule binding; protein serine kinase activity; protein serine/threonine kinase activity; protein kinase activity
Biological process: brain development; cytoskeleton organization; intracellular signal transduction; protein phosphorylation; developmental process
Cellular component: microtubule cytoskeleton; neuron projection; neuronal cell body; plasma membrane; axon; cytoskeleton; dendrite; membrane
Genetic constraint (gnomAD): Loss-of-function variants: 35 observed, 122.31 expected, observed/expected ratio (o/e) 0.29, 90% interval 0.22 to 0.38. The upper end of that interval is the gene's LOEUF score, 0.38, which puts it in group 1 of 6, group 1 being the genes least tolerant of losing a copy. Missense variants: 1,507 observed, 2,062.8 expected, observed/expected ratio (o/e) 0.73, 90% interval 0.7 to 0.76. Synonymous variants: 923 observed, 882.81 expected, observed/expected ratio (o/e) 1.05, 90% interval 0.99 to 1.1.
Homologues: Orthologues: chimpanzee MAST1 (99% identical), macaque MAST1 (99% identical), pig MAST1 (96% identical), dog MAST1 (96% identical), mouse Mast1 (94% identical), rat MAST1 (94% identical), guinea pig MAST1 (89% identical), zebrafish mast1a (69% identical), zebrafish mast1b (67% identical), tropical clawed frog mast1 (65% identical), Drosophila melanogaster dop (43% identical), Caenorhabditis elegans kin-4 (35% identical), and 4 more. Paralogues in human: MAST2 (60% identical), MAST4 (57% identical), MAST3 (49% identical), LATS1 (14% identical), LATS2 (14% identical), DMPK (12% identical), SGK1 (11% identical), SGK3 (10% identical), MASTL (10% identical), STK32C (9% identical), STK32B (8% identical), SGK2 (8% identical), and 1 more.
Diseases named in the same sentence as MAST1 in open-access papers:
MAST1 is named in the same sentence as 35 diseases in open-access papers, as found by Europe PMC text mining. Sharing a sentence is not in itself a finding about the gene and the disease. The quoted sentences say what the papers report.
breast carcinoma (13 papers, 2013 to 2025). "Non-parametric spearmen correlation revealed a positive correlation between USP28 and MAST1 expression in lung cancer (Spearman’s rho = 0.81); breast cancer (Spearman’s rho = 0.61) and colon cancer (Spearman’s rho = 0.76)." (PMID 38498222, 2024). "High expression of USP28 and MAST1 was observed in lung cancer, breast cancer and colon cancer samples." (PMID 38498222, 2024). "We observed significantly high expression patterns for both USP1 and MAST1 in lung cancer (n = 32), colon cancer (n = 32), and breast cancer (n = 21) samples." (PMID 35966591, 2022). "In some breast cancer cells, MAST1 and MAST2 are fused with other proteins through recurrent gene rearrangements; these fusion proteins act as putative tumorigenic drivers." (PMID 30773781, 2019). "Methylation pattern of MAST1, PRDM14, and ZNF177 may represent new diagnostic biomarkers for breast cancer, while methylation of ADCY4, CPXM1, DNM3, PRDM14, PRKCB, and ZNF177 may hold prognostic potential for breast cancer." (PMID 33499882, 2021). "Interestingly, during preparation of this manuscript, recurrent gene rearrangements involving MAST2 and MAST1 were identified in breast cancer cell lines and tissues." (PMID 23717670, 2013). "Somatic alterations in the genes for MAST1 and MAST2 were discovered and characterized in material obtained from breast cancer samples." (PMID 37569286, 2023). "The recurrent rearrangement and overexpression of MAST1 and MAST2 gene fusions reportedly have proliferative effects in breast cancer." (PMID 35966591, 2022). "Results from additional validation analyses showed that MAST1, PRDM14, and ZNF177 had high sensitivity, specificity, and accuracy for breast cancer diagnosis." (PMID 33499882, 2021). "In summary, we have identified and independently validated abnormal DNA methylation patterns in MAST1, PRDM14, and ZNF177 as potential biomarkers for breast cancer diagnosis." (PMID 33499882, 2021). "MAST2 gene rearrangements were previously noted in some breast cancers, and overexpression of MAST2 (or MAST1) gene fusions in breast epithelial cells led to increased proliferation in vitro and in vivo." (PMID 33902690, 2021). "As expected, methylation levels of ADCY4, CPXM1, DNM3, GNG4, MAST1, PRDM14, and ZNF177 were found to be increased in breast cancer, and all with p values lower than 0.001." (PMID 33499882, 2021). "Overall, we found that MAST1, PRDM14, and ZNF177 had high sensitivity, specificity, and accuracy for the diagnosis of breast cancer." (PMID 33499882, 2021). "However, the role of MAST1, PRDM14, and ZNF177 in diagnosis and prognosis of breast cancer remains unclear." (PMID 33499882, 2021). "Our findings add a new layer of evidence to the epigenetic landscape of breast cancer, providing convincing clues that MAST1, PRDM14, and ZNF177 are differentially methylated in breast cancer, as well as that they may serve as potential drivers and biomarkers for breast cancer." (PMID 33499882, 2021).
lung carcinoma (5 papers, 2019 to 2024). "A pedigree study reported that MAST1 variants are associated with lung cancer." (PMID 30773781, 2019). "Besides, MAST1 was significantly negatively associated with CHIP expression in lung cancer." (PMID 36199626, 2022). "From a differential analysis of the lung cancer-related microarray GSE74706, we found that MAST1 was highly expressed in lung cancer samples as compared with the normal samples." (PMID 36199626, 2022). "Furthermore, USP1-knockout A549 lung cancer cells were generated to validate the deubiquitinating activity of USP1 on MAST1 abundance." (PMID 35966591, 2022). "Besides, MAST1 has been suggested to function as an oncogenic driver to lung cancer." (PMID 36199626, 2022).
developmental delay (3 papers, 2023 to 2025). "MAST1 is responsible for an ultrarare condition characterised by global developmental delay and cognitive decline; our index case added ataxia to the list of concomitant associated symptoms." (PMID 38003592, 2023). "Unlike MAST1 variants, which are associated with megalencephaly and corpus callosum anomalies, our patient's MAST4 variant correlates with delayed myelination and developmental delay, without structural malformations." (PMID 40656202, 2025).
Ataxia (2 papers, 2022 to 2023). Ataxia refers to impaired coordination of voluntary muscle movement. "With MD-548, we describe the novel MAST1 c.1672G>C mutation, expanding the clinical picture of this ultrarare neurodevelopmental disorder, suggesting that ataxia may be more frequently present but masked as persistent hypotonia in other cases." (PMID 38003592, 2023).
neuroblastoma (2 papers, 2020 to 2024). Neuroblastoma (NB) is the most common solid, extracranial childhood tumor. "MAST1, a member of the microtubule‐associated serine/threonine kinase family, contributes to neuronal differentiation and cell cycle exit by regulating P27 in neuroblastoma cells." (PMID 32291963, 2020). "MAST1 played a role in modulating neuronal differentiation and cell cycle exit through P27 in neuroblastoma cells." (PMID 39318189, 2024). "We report that MAST1 is upregulated during neuronal differentiation of the human neuroblastoma cell line, SH‐SY5Y." (PMID 32291963, 2020).
ovarian carcinoma (2 papers, 2021 to 2022). A malignant neoplasm originating from the surface ovarian epithelium. "Recent research has revealed that microtubule-associated serine/threonine-protein kinase 1 (MAST1) plays an essential role in driving post-target cisplatin-resistance mechanisms in many cancers, including head and neck, lung, and ovarian cancers." (PMID 35966591, 2022). "MAST1 levels were higher in ovarian cancer patients with high GR activity compared to patients with low GR activity, which was determined by transcriptome signature of glucocorticoid regulated genes." (PMID 34400618, 2021). "In addition, the expression level of MAST1 was increased upon cisplatin treatment in cancer cell lines including cervical cancer KB-3-1 and ovarian cancer A2780." (PMID 34400618, 2021).
autism (1 paper, 2021). Persistent deficits in social interaction and communication and interaction as well as a markedly restricted repertoire of activity and interest as well as repetitive patterns of behavior. "MAST1 is essential for correct brain development and MAST1 substitutions are present in patients with autism and microcephaly, suggesting that mutations in this gene might be involved in neurodevelopmental diseases." (PMID 34835087, 2021).
diabetes mellitus (1 paper, 2015). A metabolic disorder characterized by abnormally high blood sugar levels due to diminished production of insulin or insulin resistance/desensitization. "MAST1 is an important paralog of MAST245, and phosphorylation of DMD or UTRN may modulate their affinities for associated proteins, and thus may also be associated with diabetes mellitus." (PMID 26399914, 2015).
endometrial cancer (1 paper, 2022). Primary or metastatic malignant neoplasm involving the endometrium (mucous membrane that lines the endometrial cavity). "Using univariate Cox regression and Least absolute shrinkage and selection operator (LASSO), seven kinases (ALPK2, CAMKV, TTK, PTK6, MAST1, CIT, and FAM198B) were identified to establish a prognostic model of endometrial cancer." (PMID 36158685, 2022).
Epileptic encephalopathy (1 paper, 2023). A condition in which epileptiform abnormalities are believed to contribute to the progressive disturbance in cerebral function. "Few cases with MAST1 mutations have been reported with atypical presentations, such as absence of cerebellar hypoplasia, predominant bilateral polymicrogyria, dysmorphic features, short stature, epileptic encephalopathy, and hypogonadotropic hypogonadism." (PMID 38003592, 2023).
head and neck cancer (1 paper, 2021). A primary or metastatic malignant neoplasm affecting the head and neck. "In our study, we provide clinical evidence that GR nuclear translocation positively correlates with MAST1 expression and platinum resistance in head and neck cancer patients." (PMID 34400618, 2021).
pancreatic cancer (1 paper, 2024). "Accordingly, we further investigated the effects of MAST1, the host gene of miR-6794-3p, on pancreatic cancer cell invasion and migration." (PMID 39430246, 2024). "Accordingly, we examined the effects of MAST1 on pancreatic cancer cell invasion and migration." (PMID 39430246, 2024). "Since miR-6794-3p is located between exons 9 and 10 of MAST1, we investigated whether expression of the host gene could affect pancreatic cancer cell invasion and migration." (PMID 39430246, 2024). "However, we found that MAST1 and its encoded protein product did not appear to be associated with the invasion or migration of pancreatic cancer cells." (PMID 39430246, 2024). "We found that overexpression of MAST1 in pancreatic cancer cells did not affect the gene expression of miR-6794-3p, or vice versa." (PMID 39430246, 2024). "Furthermore, expression of MAST1 does not alter the invasion or migration of pancreatic cancer cells." (PMID 39430246, 2024). "Moreover, MAST1 upregulation did not restore the miR-6794-3p-induced suppression of pancreatic cancer cell invasion and migration." (PMID 39430246, 2024).
tooth agenesis (1 paper, 2023). A tooth disease characterized by failure to develop one or more missing teeth. "Pathogenic variants in these genes lead to Tooth agenesis (PAX9) and Mega-corpus-callosum syndrome with cerebellar hypoplasia and cortical malformations (MAST1)." (PMID 36651276, 2023).
vitiligo (1 paper, 2025). Generalized well circumscribed patches of leukoderma that are generally distributed over symmetric body locations and is due to autoimmune destruction of melanocytes. "However, there is currently no direct evidence indicating that MAST1 is the causative gene for vitiligo." (PMID 40948579, 2025). "Finally, qPCR was used to detect the expression of FLJ21901 and MAST1, of which the first-ranked gene could provide potential targets for the treatment of vitiligo." (PMID 40948579, 2025). "Compared with the skin tissue, it significantly increased the mRNA expression of vitiligo skin tissues FLJ21901, and MAST1 mRNA expression was significantly reduced." (PMID 40948579, 2025). "Real-time quantitative PCR was used to detect the relative mRNA expressions of differentially expressed genes FLJ21901 and MAST1 between lesion and nonlesion tissues in 6 patients with vitiligo." (PMID 40948579, 2025).
cancer (14 papers, 2020 to 2025). A tumor composed of atypical neoplastic, often pleomorphic cells that invade other tissues. "MAST1 has also been implicated as a target for cancer therapy since its upregulation can often lead to cancer." (PMID 40299535, 2025). "USP28 regulates the protein level of microtubule-associated serine/threonine kinase 1 (MAST1), a common kinase whose expression is elevated in several cisplatin-resistant cancer cells." (PMID 38498222, 2024). "Microtubule-associated serine/threonine-protein kinase 1 (MAST1) was recently reported as a key driving factor in the development of cisplatin resistance in many cancer types." (PMID 38498222, 2024). "Since the MAST kinases are known to be associated with different cancer types, further studies addressed the biological role of these kinases and identified MAST1 as a key regulator for cisplatin resistance in human cancer cells." (PMID 37569286, 2023). "The expression of microtubule-associated serine/threonine kinase 1 (MAST1) is a primary factor driving cisplatin-resistance in cancers by rewiring the MEK pathway." (PMID 35966591, 2022). "USP1 promotes MAST1-mediated MEK1 activation as an underlying mechanism that contributes to cisplatin-resistance in cancers." (PMID 35966591, 2022). "Previous studies reported that abnormal MAST1 expression is significantly associated with worse cancer prognosis." (PMID 33499882, 2021). "Microtubule-associated serine/threonine kinase 1 (MAST1) mediates cisplatin resistance in human cancers." (PMID 33935743, 2021). "However, when the MAST1 promoter carried the GR binding-deficient mutation in GRE, MAST1 promoter activity was abolished in cancer cells." (PMID 34400618, 2021). "Notably, CHIP could negatively regulate microtubule-associated serine/threonine kinase 1 (MAST1) to induce MAST1 ubiquitination and degradation, and Hsp90β could interact with and stabilize MAST1 in cisplatin-resistant cancer cells." (PMID 36199626, 2022). "We identified a microtubule-associated serine/threonine kinase 1 (MAST1) as a common essential driver for cisplatin resistance that provides a post-target cisplatin resistance mechanism through managing the pro-apoptotic pathway in human cancers, including lung, ovarian, and head and neck cancers." (PMID 34400618, 2021). "The combination of cisplatin treatment with lestaurtinib, a MAST1 inhibitor, potentially inhibited MAST1 kinase activity and sensitized several cancer types to cisplatin." (PMID 38498222, 2024). "We further analyzed the expression of USP28 and MAST1 in a wide range of cancer cell lines using the Cancer Cell Line Encyclopedia (CCLE) database." (PMID 38498222, 2024). "We recently performed CRISPR/Cas9-based genome-wide screening for DUBs that regulate MAST1 protein levels as well as DUBs that confer cisplatin resistance in cancers." (PMID 38498222, 2024). "The expression pattern of USP28 and MAST1 showed a positive correlation across a panel of tested cancer cell lines and human clinical tissues." (PMID 38498222, 2024). "Previously, we reported that USP1 regulated the MAST1-mediated MEK pathway in cisplatin-resistant cancer cells." (PMID 38498222, 2024). "We used the TCGA database to evaluate the normal-tumor matched mRNA expression level of USP28 and MAST1 in different cancer types." (PMID 38498222, 2024). "The expression level and protein turnover of MAST1 is a major factor driving cisplatin resistance in many cancer types." (PMID 38498222, 2024). "Depletion of USP28 destabilized MAST1 protein levels and also sensitized cisplatin-resistant cancer cells for cisplatin-mediated cytotoxicity." (PMID 38498222, 2024). "We demonstrated that USP28 interacts and regulate MAST1 protein stabilization in cisplatin-resistant cancer cells." (PMID 38498222, 2024). "A recent study revealed that the stability of MAST1 is also enhanced by the deubiquitinase USP1 in cisplatin-resistant cancer cells." (PMID 37569286, 2023).